EGFR (epidermal growth factor receptor)
Diseases named in the same sentence as EGFR in open-access papers (continued):
Sharing a sentence is not in itself a finding about the gene and the disease.
pancreatic cancer (continued). "However, we demonstrated that in pancreatic cancer, USP8 knockdown and USP8 inhibition did not affect EGFR expression levels." (PMID 36539510, 2023). "Moreover, EGFR expression and activation are not involved in AGR2 pro-oncogenic roles in PANC-1 pancreatic cancer cells." (PMID 33413231, 2021). "Another human RNase called hRNase 5 acts as an EGFR ligand and a serum biomarker to predict EGFR inhibitor response in pancreatic cancer, but EGF fails to have such predictive function although the binding affinity of hRNase 5 to EGFR is about 23-fold less than EGF for EGFR binding." (PMID 33986289, 2021). "New treatments targeting known oncogenes, or growth factors, in pancreatic cancer such as K-Ras, vascular endothelial growth factor (VEGF) and epidermal growth factor (EGF)/epidermal growth factor receptor (EGFR) have mostly failed and do not provide survival benefits." (PMID 27240340, 2016). "Considering that AZD8055 could induce AKT inhibition, we found that EGFR, but not other RTKs, could be potently upregulated by AZD8055 in pancreatic cancer cells." (PMID 25654224, 2015). "In agreement with previous studies in human pancreatic cancer cells (Panc-1) we found that neurotensin-induced ERK activation and DNA synthesis in the colon cancer cells HCT116 was mainly dependent on PKC and did not involve EGFR transactivation." (PMID 21961726, 2011). "Since the relative significance of EGFR and NTR1 in regard to tumor cell proliferation and dissemination has not been elucidated for the pancreatic cancer cell lines so far, we compared the dependence of the expression of both receptors on cell density and pHe." (PMID 24212612, 2011). "EGFR phosphorylation was detected in neither A431 cells (a human epidermoid carcinoma cell line; PTPRHhigh), HepG2 cells (a human hepatocellular carcinoma cell line; PTPRHlow), nor MIA-PaCa-2 cells (a human pancreatic carcinoma cell line; PTPRHlow) in the steady-state condition." (PMID 34187934, 2021). "Interestingly, in the 3 erlotinib-resistant pancreatic tumors studied that displayed significantly lower Mig6 expression (PANC140, 294, and 215), IHC labeling revealed that 2 of these 3 xenograft lines did not express EGFR." (PMID 23935914, 2013). "The combination of Src and EGFR inhibition with Gemcitabine treatment in STAT3-mediated therapy-resistant pancreatic tumors was also effective at inhibiting the growth of xenografts of both therapy-sensitive and -resistant pancreatic cancer cells in vivo without increasing toxicity." (PMID 24499623, 2013).
colon carcinoma (926 papers, 1998 to 2026). "It is noteworthy that, within the four colon cancer cell types that have so far been confirmed in vitro as rTBL-1-responsive, only MC-38 cells harbor a mutation in EGFR (G1103C) at the level of the C-terminal tail." (PMID 40006027, 2025). "A poor prognosis has been linked to 60–80% of colonic tumors with overexpressed EGF receptor (EGFR)." (PMID 39590368, 2024). "Previous research has demonstrated that colon tumors are more frequently associated with microsatellite instability, overexpression of epiregulin, chromosomal instability, and epidermal growth factor receptor amplification compared to rectal tumors." (PMID 38978992, 2024). "For BRAF (V600E) mutated colon cancer, vemurafenib feedback activates EGFR, although it can inhibit BRAF (V600E)." (PMID 36678567, 2023). "As is known to all, KRAS mutated colon cancer acquired resistance to anti-EGFR drugs such as cetuximab due to constitutively active of KRAS protein." (PMID 38097680, 2023). "RAS and BRAF mutations are not only associated with poor prognosis in colon cancer but also show resistance to anti-epidermal growth factor receptor (EGFR) agents such as cetuximab and panitumumab." (PMID 36819360, 2023). "In a previous publication, afatinib (an epidermal growth factor receptor inhibitor) effectively decreased the viability of BRAFV600E mutant colon cancer either in EGFR-wildtype or EGFR-mutated cells." (PMID 36658200, 2023). "Fisetin (30–120 μM) inhibits COX-2 and the Wnt/β/ EGFR/ NF-κB signaling pathways, which cause apoptosis in colon cancer cells." (PMID 37565061, 2023). "Collectively, our findings indicate that Sia deacetylation renders lung and colon cancer cells susceptible to EGFR therapeutics and provide insights for future therapeutic interventions." (PMID 37687086, 2023). "KRAS mutation test showed KRAS wild-type colon cancer, but she refused anti-epidermal growth factor receptor therapy." (PMID 37872388, 2023). "Whereas left-sided colon cancer was more likely associated with EGFR mutations and HER2 amplification." (PMID 37933355, 2023). "In colon carcinoma cells, calcitriol reduced EGFR expression and augmented SPRY expression, encoding a physiological antagonist to the EGF-triggered cascade." (PMID 36364774, 2022). "EGFR mutations and overactivated EGFR signaling pathways are frequently associated with several types of cancers, including lung, head and neck, and colon cancer." (PMID 36359754, 2022). "Since release of the guidance and excluding the ONCO/Reveal Diagnostic Lung and Colon Cancer Assay, an additional two EGFR CDx devices were identified, bringing the total EGFR CDx devices appropriate for the same therapeutic class labeling to five." (PMID 35689144, 2022). "The TGFα-EGFR pathway in both cancer-associated endothelial cells and cancer cells themselves is essential in the development of colon cancer." (PMID 35402265, 2022). "A previous study reported that EGCG alters plasma membrane organization and causes internalization of EGFR, resulting in the suppression of colon cancer cell growth." (PMID 35893779, 2022). "Previous studies have shown that KRAS mutation can act as a biomarker of EGFR-targeted monoclonal antibody resistance in colon cancer patients and is associated with metastasis and poor prognosis." (PMID 35479956, 2022). "K-Ras mutations occur at high frequencies in colon cancer cells, and they result in constitutive activation of signaling pathways downstream of EGFR, including Ras/MAPK and PI3K-Akt pathways." (PMID 36103569, 2022). "In colon cancer, loss of Dsg2 leads to a compensatory increase in Dsc2 expression and the increased Dsc2 suppresses cell proliferation by inhibition of EGFR downstream signaling such as Src." (PMID 32989241, 2021).
colon carcinoma (continued). "The reduced expression of EGFR is associated with a decrease of cell proliferation in colon cancer cells." (PMID 33513799, 2021). "Exosomal PVT1 promotes colon cancer metastasis through its association with EGFR and VEGFA expression." (PMID 34336125, 2021). "Among the therapeutic targets for cancer, the abnormal expression of the epidermal growth factor receptor (EGFR) is strongly associated with various malignancies such as breast, ovarian, non-small-cell lung, prostate, and colon cancers." (PMID 34122069, 2021). "High expression of EGFR or IGFBP2 was associated with poor prognosis while high expression of SRC or SRC_pY527 predicted superior survival in colon cancer." (PMID 33758598, 2021). "As BRAF is downstream of RAS in the MAPK/ERK signaling pathway, mutated BRAF is assumed to have the same resistance to the anti-EGFR agent as to the RAS-mutated colon tumor." (PMID 33254149, 2020). "The transit-amplifying colon cancer was associated with the clinical benefit of EGFR inhibitor cetuximab or c-MET inhibitor treatment." (PMID 31596728, 2019). "ST6Gal-mediated sialylation of EGFR has been shown to cause chemoresistance to gefitinib in colon cancer cells." (PMID 30187356, 2018). "Although the development of an alternative approach is in need for the patients with RAS mutations, more than 55–65% of colon cancer patients who express wild-type KRAS will still benefit from anti-EGFR therapies." (PMID 30158525, 2018). "The combination of a BRAF inhibitor with an EGFR inhibitor was recently tested in BRAF-mutated colon cancer patients with very modest therapeutic results." (PMID 29652830, 2018). "Right-sided colon cancers had higher rates of microsatellite instability, more frequent aberrant activation of the EGFR pathway including higher BRAF and PIK3CA mutation rates, and increased mutational burden compared to left-sided colon and rectal cancers." (PMID 29156800, 2017). "Studies have further reported causal role of the HDACi in regulating EGFR expression (mRNA transcription) and associated signaling using colon cancer cells." (PMID 29152115, 2017). "Overall, we here demonstrtae a role for HDAC-4 in regulating differentiation and growth properties of colon cancer cells in causal association with EGFR/ERK1/2-signaling and claudin-2 expression." (PMID 29152115, 2017). "For example, mutations in the KRAS gene are associated with resistance to anti-EGFR drugs, which are approved selectively for colon cancer patients with wild type (WT) KRAS." (PMID 28420162, 2017). "Accumulating evidences indicated that both c-Met and EGFR were overexpressed by 78 to 80% of colon cancers, which were associated with poor outcome." (PMID 28086832, 2017). "Our findings show that overproduction of HGF can cause primary resistance to EGFRi in colon cancer cells and suggest that such patients would benefit from combined therapy with inhibitors of EGFR and HGF." (PMID 27121052, 2016). "For example, while melanoma patients harboring BRAF V600E mutation respond well to BRAF inhibitors, colon cancer patients with the same mutation often don’t due to the feedback activation of EGFR and its associated signaling pathway." (PMID 26916442, 2016). "The detailed functional consequences of EGFR mutations in prostate and colon cancer are still unclear." (PMID 25794154, 2015). "Although its biological function remains poorly understood, REG4 is reported to be a potent activator of the EGFR/Akt/AP-1 signaling pathway in colon cancer cells and closely linked with the inhibition of apoptosis." (PMID 26077911, 2015). "Inappropriate activation of epidermal growth factor receptor (EGFR) plays a causal role in many cancers including colon cancer." (PMID 25301722, 2014). "In order to further examine the efficacy of cetuximab, we expanded our studies by generating xenograft mouse models with either SW48 or HCT8 colon cancer cells, which harbor either EGFR G719S or KRAS G13D mutation, respectively." (PMID 24894453, 2014).
colon carcinoma (continued). "Overexpression and constitutive activation of EGFR have been associated with a poor prognosis in colon cancer patients." (PMID 24874286, 2014). "KRAS: The important therapeutic KRAS mutation in colon cancer was detected in ID.3 and ID.6 (exon 2 aa12), two EGFR wildtype samples." (PMID 23922754, 2013). "For example, membrane proteins like Fas death receptor, EGFR and ß1-integrin are known to exhibit variant sialylation that can affect chemo-sensitivity, metastasis and migration of colon tumor cells." (PMID 23468914, 2013). "Here we explore the issues that lead to delay in routine implementation of these kinds of tests by discussing the examples of K-ras mutation testing in colon cancer and EGFR mutation testing in lung cancer." (PMID 22666589, 2012). "Aberrant expression or activation of EGFR has been strongly linked to the etiology of several human epithelial cancers, including colon cancer." (PMID 22761867, 2012). "The tumor sample from a patient with colon cancer (PD) was EGFR mutation positive, with a normal EGFR copy number and K-ras mutation positive." (PMID 22878519, 2012). "For example insertions in APC are associated with colon tumors, while EGFR insertions are associated with liver tumors." (PMID 22748055, 2012). "Similar to the story of EGFR monoclonal antibodies in colon cancer treatment, K-ras mutation can nullify the effect of a TKI." (PMID 22666589, 2012). "KRAS mutant tumours did not demonstrate mutations in EGFR consistent with previous reports in both NSCLC and colon carcinoma which suggest that KRAS mutations predict resistance to EGFR antagonists." (PMID 21385341, 2011). "Gain and loss of function approaches in breast and colon cancer cells demonstrated that SRCIN1 inhibits EGFR and Erk1/2 signaling, blocking scatter and proliferation of cancer cells." (PMID 21931769, 2011). "We have demonstrated that proliferation of colon cancer cells, stimulated with signals from EGFR, is mediated by loss of tumor suppressor FOXO3 activity." (PMID 21639915, 2011). "The nuclear localization of EGFR has been linked to more aggressive tumor types and increased nuclear localization of CysLT1R has also been observed in colon cancer cells." (PMID 22194989, 2011). "Epidermal growth factor receptor expression has been shown to be associated with disease recurrence and poor survival in colon cancer." (PMID 20842128, 2010). "Expression of the epidermal growth factor receptor (EGFR) has been associated with outcome in colon cancer." (PMID 15870719, 2005). "Additionally, in RAS/RAF wild colon cancer, it has been reported that some tumors acquiring resistance to anti-EGFR antibody therapy harbor new mutations in the RAS-MAPK signaling pathway." (PMID 40546348, 2025). "In addition, right-sided colon tumors, which have increased prevalence of KRAS and BRAF mutations and are associated with worse prognosis compared to left-sided colon tumors, respond poorly to EGFR inhibition." (PMID 38672633, 2024). "Given the pivotal roles of SRC and EGFR as oncogenes impacting colon cancer development, exploring Tks4’s role in colon cancer becomes imperative for a comprehensive understanding of the pathomechanisms underlying colon cancer formation." (PMID 39234565, 2024). "However, several EGFR inhibitors have been used to treat many types of cancers, such as pancreatic, lung, breast, thyroid, and colon cancer, caused by the up-regulation of EGFR." (PMID 38266021, 2024). "We also found that rTBL-1 retains its cytotoxic apoptosis-inducing effect on colon cancer cells via influencing epidermal growth factor cell receptor (EGFR) signaling pathways and principally by causing partial receptor degradation and activation of p38 MAPK signaling." (PMID 39769023, 2024). "Furthermore, mutation and upregulation of the ErbB signaling receptors (i.e., EGFR) have been associated with different types of cancers, such as breast and colon cancer." (PMID 37108604, 2023).
colon carcinoma (continued). "Indeed, several studies reported an association between EGFR overexpression and malignancies, such as lung, breast, and colon cancers." (PMID 37892022, 2023). "Similarly, the identification of aberrant signalling downstream of (Epidermal growth factor receptor) EGFR mutation and (Receptor tyrosine-protein kinase erbB-2) Her2 amplification opened new therapeutic windows in lung, breast and colon cancer." (PMID 37569364, 2023). "Similarly, a secondary EGFR mutation in the ectodomain, S492R, results in cetuximab resistance by preventing the EGFR antibody from binding its target site in colon cancer." (PMID 35814435, 2022). "However, BRAF inhibitor monotherapy showed a low response rate in BRAF-MT mCRC because rebound feedback with increased signaling through the epidermal growth factor receptor (EGFR) pathway after BRAF inhibition occurs in colon cancer." (PMID 35625987, 2022). "In order to identify the cells that can hypothetically benefit from the administration of EGFR-targeted therapies, we initially evaluated the mutational status of EGFR downstream pathways of 13 commercially available colon cancer cell lines, as well as a normal intestinal mucosa cell line." (PMID 33233823, 2020). "The right side colon cancer was found to have more BRAF mutation than left side colon cancer, which might cause the resistant to anti-EGFR therapy and worsen the prognosis." (PMID 32547859, 2020). "EGFR activation upregulated claudin-2 in colon cancer cells, and claudin-2 expression was decreased in the colon of waved-2 mice that have EGFR activation deficiency (see also Section 3.2 on the effects of EGFR on claudin-2)." (PMID 31726679, 2019). "However, due to the mutation and over-expression of EGFR/RAS/BRAF, the abnormal activation of EGFR/RAS pathway occurs frequently in colon cancers and is associated with a poor prognosis and drug resistance." (PMID 30185207, 2018). "Ras is downstream of EGFR, and k-ras mutations frequently occur in colon cancer." (PMID 29378529, 2018). "The higher rate of activating PIK3CA mutations and PTEN loss in left- and right-sided colon cancers compared to rectal cancers could contribute to a lower response to anti-EGFR therapies in some colon cancers and supports the use of alternative treatments." (PMID 29156800, 2017). "This suggests that the combination of RT11-i and an anti-EGFR antibody might be an effective clinical strategy for patients with advanced colon cancer harbouring oncogenic KRas mutations." (PMID 28489072, 2017). "Furthermore, colon cancer can be receptive or refractory to the anti-EGFR therapy based upon the status of K-Ras mutation." (PMID 29152115, 2017). "Our findings demonstrate that overproduction of HGF can underlie primary resistance to EGFRi in colon cancer cells that harbor WT KRas and suggest that these patients may benefit from combined therapy with inhibitors of EGFR and HGF." (PMID 27121052, 2016). "The overexpression of EGFR was associated with breast, lung and colon cancers." (PMID 27875996, 2016). "Notably, feedback gene expression upregulation has been reported with other inhibitors such as a BRAF inhibitor which causes upregulation of EGFR gene expression in colon cancer 26, in this case leading to therapeutic resistance." (PMID 26275572, 2015). "Importantly, hyperactivation of SRC/EGFR signaling triggered by loss of PTPRO leads to high resistance of colon cancer to EGFR inhibitors." (PMID 25301722, 2014). "Src kinase can interact with and phosphorylate RTKs including EGFR, and regulate proliferation through the Erk/MAP kinase pathway; overexpression or increased activation of Src is found in several cancers including breast and colon cancers and is frequently linked with high EGFR levels." (PMID 24295852, 2014). "Furthermore, EGFR phosphorylation at Y845 has been proposed as a diagnostic marker to assess gefitinib sensitivity in colon cancers." (PMID 25301722, 2014).